CWF19L2 (CWF19 like cell cycle control factor 2)
Synonyms: FLJ32343
Tractability: Small molecule: a structure with a bound ligand is known. PROTAC: UniProt records ubiquitination sites on it; ubiquitination databases record sites on it; its protein half-life has been measured.
Gene: Protein-coding gene on chromosome 11 (107,321,601 to 107,457,842, reverse strand). Ensembl gene ENSG00000152404.
Subcellular location (Human Protein Atlas): Nuclear speckles; Cytosol
Pathways (Reactome):
Metabolism of RNA: mRNA Splicing - Major Pathway
Gene Ontology:
Molecular function: protein binding
Biological process: mRNA splicing, via spliceosome
Cellular component: nucleus; post-mRNA release spliceosomal complex; spliceosomal complex; nucleoplasm
Genetic constraint (gnomAD): Loss-of-function variants: 39 observed, 49.23 expected, observed/expected ratio (o/e) 0.79, 90% interval 0.61 to 1.03. The upper end of that interval is the gene's LOEUF score, 1.03, which puts it in group 4 of 6, group 1 being the genes least tolerant of losing a copy. Missense variants: 627 observed, 584.61 expected, observed/expected ratio (o/e) 1.07, 90% interval 1 to 1.15. Synonymous variants: 195 observed, 192.17 expected, observed/expected ratio (o/e) 1.01, 90% interval 0.9 to 1.14.
Homologues: Orthologues: chimpanzee CWF19L2 (99% identical), macaque CWF19L2 (96% identical), dog CWF19L2 (85% identical), pig CWF19L2 (84% identical), rabbit CWF19L2 (82% identical), rat Cwf19l2 (74% identical), mouse Cwf19l2 (73% identical), tropical clawed frog cwf19l2 (57% identical), zebrafish cwf19l2 (51% identical), Drosophila melanogaster CG9213 (29% identical), Caenorhabditis elegans cwf-19L2 (19% identical), zebrafish cwf19l2 (19% identical). Paralogues in human: CWF19L1 (13% identical).
Diseases named in the same sentence as CWF19L2 in open-access papers:
CWF19L2 is named in the same sentence as 4 diseases in open-access papers, as found by Europe PMC text mining. Sharing a sentence is not in itself a finding about the gene and the disease. The quoted sentences say what the papers report.
breast carcinoma (1 paper, 2025). "Other co-expressed genes such as BMF, CD53, PIK3R1, and CWF19L2 have also been reported in breast cancer studies." (PMID 40282270, 2025). "In contrast, the expression levels of PIK3R1, PNPLA2, ATOH8, TTC23, and CWF19L2 were dramatically lower in breast cancer samples than in healthy controls (p < 0.05)." (PMID 40282270, 2025).
male infertility (1 paper, 2024). The inability of the male to effect fertilization of an ovum after a specified period of unprotected intercourse. "Deletion of FBXW7 in germ cells suppresses differentiation by upregulation of MYC and CCNE1 and leads to male infertility, which is similar to the phenotype of Cwf19l2‐SKO mice in this study." (PMID 38889293, 2024). "Our results demonstrated that deletion of CWF19L2 in germ cells caused spermatogenesis failure and complete male infertility, but the knockout of CWF19L2 in Sertoli cells did not affect fertility." (PMID 38889293, 2024).
Obesity (1 paper, 2011). Accumulation of substantial excess body fat. "A homolog to ACOT11 in mouse has been associated with obesity, but the function of CWF19L2 is unknown." (PMID 22384316, 2011).
CWF19L2 also shares sentences with these, for which no sentence is quoted: tumor (1 paper).